TMEM209 (transmembrane protein 209)
Description:
Nuclear envelope protein which in association with NUP205, may be involved in nuclear transport of various nuclear proteins in addition to MYC.
Synonyms: FLJ14803; NET31
Tractability: Antibody: UniProt predicts a signal peptide or a membrane-spanning region. PROTAC: ubiquitination databases record sites on it; its protein half-life has been measured.
Gene: Protein-coding gene on chromosome 7 (130,164,713 to 130,207,770, reverse strand). Ensembl gene ENSG00000146842.
Subcellular location: Membrane; Nucleus envelope; Golgi apparatus; Cytoplasm
Subcellular location (Human Protein Atlas): Nuclear membrane; Nuclear speckles; Vesicles
Gene Ontology:
Cellular component: cytoplasm; Golgi apparatus; nuclear envelope; membrane
Genetic constraint (gnomAD): Loss-of-function variants: 54 observed, 60.27 expected, observed/expected ratio (o/e) 0.9, 90% interval 0.72 to 1.12. The upper end of that interval is the gene's LOEUF score, 1.12, which puts it in group 4 of 6, group 1 being the genes least tolerant of losing a copy. Missense variants: 551 observed, 629.72 expected, observed/expected ratio (o/e) 0.87, 90% interval 0.81 to 0.94. Synonymous variants: 221 observed, 226.06 expected, observed/expected ratio (o/e) 0.98, 90% interval 0.88 to 1.09.
Homologues: Orthologues: chimpanzee TMEM209 (99% identical), macaque TMEM209 (99% identical), dog TMEM209 (98% identical), pig TMEM209 (97% identical), rabbit TMEM209 (96% identical), guinea pig TMEM209 (95% identical), mouse Tmem209 (95% identical), rat Tmem209 (95% identical), tropical clawed frog tmem209 (70% identical), zebrafish tmem209 (69% identical), Drosophila melanogaster CG6479 (28% identical), Caenorhabditis elegans B0464.6 (24% identical).
Diseases named in the same sentence as TMEM209 in open-access papers:
TMEM209 is named in the same sentence as 5 diseases in open-access papers, as found by Europe PMC text mining. Sharing a sentence is not in itself a finding about the gene and the disease. The quoted sentences say what the papers report.
lung carcinoma (7 papers, 2016 to 2024). "TMEM209, which encodes a nuclear envelope protein, has been reported to be associated with lung cancer." (PMID 38305770, 2024). "NET31/TMEM209, is able to alter cancer cell growth when overexpressed in lung cancer cells and interestingly is up-regulated in lung cancer cells and normal testis that contains highly proliferative cells." (PMID 36299481, 2022). "In lung cancer cell lines it was shown that through TMEM209 stabilization of NUP205, protein levels of MYC were increased and promoted cell growth." (PMID 27115612, 2016). "Furthermore, NUP205 has been shown to promote cell growth in lung cancer through its interaction with transmembrane protein 209 (TMEM209), which stabilizes NUP205 and regulates c-Myc nuclear entry." (PMID 39080077, 2024). "Lung cancer studies posited that TMEM209 was highly expressed in tumor tissues and promoted their proliferation, implicating that TMEM209 may act as an oncogene." (PMID 39414762, 2024). "Interestingly, previous study indicated that TMEM209 stabilized NUP205 in the protein level in lung cancer cells; however, a detailed understanding of its mechanism was lacking." (PMID 39414762, 2024). "TMEM209 is a putative ortholog to the S. cerevisiae NPC membrane ring protein ScPom34 which interacts with the NPC in lung cancer cells, shows colocalization with the NPC and has been suggested as an additional NPC component, while PNET1 is a membrane ring nucleoporin." (PMID 38605598, 2024). "TMEM209 and NUP205 protein interactions, stabilizing NUP205 and increasing the level of c-Myc in the nucleus, are critical drivers of lung cancer proliferation." (PMID 34299277, 2021).
lymphoma (1 paper, 2024). A malignant (clonal) proliferation of B- lymphocytes or T- lymphocytes which involves the lymph nodes, bone marrow and/or extranodal sites. "High-throughput sequencing suggested the association of TMEM209 variants to lymphoma and genome-wide analyses indicated that TMEM209 might be a target for clonal hematopoiesis." (PMID 39414762, 2024).
tumor (1 paper, 2024). "Owing to previous research indicated that the mutation of β-catenin associated with the progression of tumor, we therefore investigated the relationship of TMEM209 expression and β-catenin’s mutation by analyzing TCGA data." (PMID 39414762, 2024). "Transmembrane protein 209 (TMEM209) involves multiple biological processes, such as substance transportation and signal transduction, and is abundantly expressed in tumor tissues." (PMID 39414762, 2024). "In the subcutaneous tumor model, the tumor volume and weight in the TMEM209 group were higher than those of the Ctrl and TMEM209+shKPNB1 groups (n = 6)." (PMID 39414762, 2024). "Finally, IHC staining of a tissue microarray (N = 129) showed that the relative expression of TMEM209 in tumor tissues (17.69 ± 12.72) was notably higher than that of the normal tissues (6.044 ± 5.895)." (PMID 39414762, 2024). "Similarly, qPCR analysis indicated a remarkable upregulation of TMEM209 mRNA in tumor tissues." (PMID 39414762, 2024). "Importantly, silencing of KPNB1 slowed the tumor development induced by TMEM209 (n = 6)." (PMID 39414762, 2024). "Functionally, TMEM209 promoted the proliferation, migration, invasion, and EMT of HCC cells in vitro and facilitated tumor growth and metastasis in xenograft models." (PMID 39414762, 2024).
TMEM209 also shares sentences with these, for which no sentence is quoted: cancer (1 paper); hepatocellular carcinoma (1).